CYP27B1 (cytochrome P450 family 27 subfamily B member 1)
Description:
A cytochrome P450 monooxygenase involved in vitamin D metabolism and in calcium and phosphorus homeostasis. Catalyzes the rate-limiting step in the activation of vitamin D in the kidney, namely the hydroxylation of 25-hydroxyvitamin D3/calcidiol at the C1alpha-position to form the hormonally active form of vitamin D3, 1alpha,25-dihydroxyvitamin D3/calcitriol that acts via the vitamin D receptor (VDR). Has 1alpha-hydroxylase activity on vitamin D intermediates of the CYP24A1-mediated inactivation pathway. Converts 24R,25-dihydroxyvitamin D3/secalciferol to 1-alpha,24,25-trihydroxyvitamin D3, an active ligand of VDR. Also active on 25-hydroxyvitamin D2. Mechanistically, uses molecular oxygen inserting one oxygen atom into a substrate, and reducing the second into a water molecule, with two electrons provided by NADPH via FDXR/adrenodoxin reductase and FDX1/adrenodoxin.
Synonyms: CYP1ALPHA; CYP27B; CYP1; P450c1; CP2B; PDDR; VDD1; VDDR; VDDRI
Tractability: Small molecule: a high-quality ligand is known; it belongs to a druggable protein family. PROTAC: a small molecule that binds it is known.
Target class: Cytochrome P450 family 27B; Cytochrome P450; Enzyme; Cytochrome P450 27B1; Cytochrome P450 family 27
Safety:
Unwanted effects reported when the protein is acted on. In parentheses: how it was acted on, where the effect was seen, and who reports it.
nephrotoxicity (source: ClinPGx)
Gene: Protein-coding gene on chromosome 12 (57,762,334 to 57,768,986, reverse strand). Ensembl gene ENSG00000111012.
Subcellular location: Mitochondrion membrane
Pathways (Reactome):
Metabolism: Vitamin D (calciferol) metabolism; Vitamins
Disease: Defective CYP27B1 causes VDDR1A
Gene Ontology:
Molecular function: calcidiol 1-monooxygenase activity; secalciferol 1-monooxygenase activity; heme binding; iron ion binding; monooxygenase activity; oxidoreductase activity, acting on paired donors, with incorporation or reduction of molecular oxygen
Biological process: bone mineralization; calcitriol biosynthetic process from calciol; calcium ion homeostasis; decidualization; G1 to G0 transition; negative regulation of cell growth; negative regulation of cell population proliferation; positive regulation of keratinocyte differentiation; positive regulation of vitamin D receptor signaling pathway; regulation of bone mineralization; response to estrogen; response to lipopolysaccharide; response to type II interferon; response to vitamin D; vitamin D metabolic process; calcium ion transport; vitamin D catabolic process; vitamin metabolic process; cellular response to vitamin D; lipid biosynthetic process; steroid metabolic process; vitamin D biosynthetic process
Cellular component: cytoplasm; mitochondrion; mitochondrial outer membrane; mitochondrial membrane
Genetic constraint (gnomAD): Loss-of-function variants: 45 observed, 52.47 expected, observed/expected ratio (o/e) 0.86, 90% interval 0.67 to 1.1. The upper end of that interval is the gene's LOEUF score, 1.1, which puts it in group 4 of 6, group 1 being the genes least tolerant of losing a copy. Missense variants: 672 observed, 690.36 expected, observed/expected ratio (o/e) 0.97, 90% interval 0.91 to 1.04. Synonymous variants: 291 observed, 296.57 expected, observed/expected ratio (o/e) 0.98, 90% interval 0.89 to 1.08.
Gene-disease validity (ClinGen):
ClinGen rates the evidence that CYP27B1 causes each of these diseases.
vitamin D-dependent rickets, type 1A (autosomal recessive): Definitive.
Homologues: Orthologues: chimpanzee CYP27B1 (99% identical), macaque CYP27B1 (96% identical), dog CYP27B1 (89% identical), pig CYP27B1 (88% identical), guinea pig CYP27B1 (85% identical), mouse Cyp27b1 (81% identical), rat Cyp27b1 (81% identical), rabbit CYP27B1 (79% identical), tropical clawed frog cyp27b1 (55% identical), zebrafish cyp27b1 (51% identical), Drosophila melanogaster sad (26% identical). Paralogues in human: CYP27A1 (39% identical), CYP27C1 (39% identical), CYP24A1 (31% identical).
Diseases named in the same sentence as CYP27B1 in open-access papers:
CYP27B1 is named in the same sentence as 201 diseases in open-access papers, as found by Europe PMC text mining. Sharing a sentence is not in itself a finding about the gene and the disease. The quoted sentences say what the papers report.
vitamin D deficiency (36 papers, 2013 to 2025). A nutritional condition produced by a deficiency of VITAMIN D in the diet, insufficient production of vitamin D in the skin, inadequate absorption of vitamin D from the diet, or abnormal conversion of vitamin D to its bioactive metabolites. "The Cyp27b1 null mouse is a model not only for CYP27B1 deficiency but also vitamin D deficiency during pregnancy and lactation, since both conditions lead to inadequate calcitriol, hypocalcemia, secondary hyperparathyroidism, and other similar effects." (PMID 38477809, 2024). "Findings from the present study suggested that NADSYN1/DHCR7 rs12785878 TT genotypes and CYP27B1 rs10877012 GT genotypes were associated with decreased risk of vitamin D deficiency." (PMID 37259065, 2023). "In a meta-analysis study, CYP2R1 and CYP27B1 genes were shown linked with different anthropometric measures of obesity and vitamin D deficiency patients." (PMID 37184736, 2023). "Our study showed that the proportion of vitamin D deficiency was higher in the NH group than in controls, and rs12785878 (NADSYN1/DHCR7) and rs10877012 (CYP27B1) are correlated with NH risk and vitamin D deficiency." (PMID 37259065, 2023). "We also found that GG allele of GC-rs7041 (p-value < 0.05) was negatively and the CA & CC alleles of CYP27B1-rs10877012 (p-value < 0.05) were positively associated with vitamin D deficiency in the surveyed children." (PMID 35256680, 2022). "Our study reports that common variants in vitamin D pathway genes (CYP27B1 and GC) were associated to vitamin D deficiency in rural and urban children of Bangladesh." (PMID 35256680, 2022). "The associations of CYP2R1, CYP24A1, and CYP27B1 gene polymorphisms with vitamin D deficiency in multiple population have been reported." (PMID 34484304, 2021). "Changes in CYP27B1 mRNA transcript levels potentially confirm the association between vitamin D deficiency and immune diseases." (PMID 33066266, 2020). "We aimed at investigating the family‐based association between SNPs of CYP2R1 and CYP27B1 and vitamin D deficiency." (PMID 30993743, 2019). "We conducted three studies including case‐control study, family‐based study, and siblings study to investigate the associations between SNPs in CYP2R1 and CYP27B1 and vitamin D deficiency." (PMID 30993743, 2019). "It was verified in this study that transmission disequilibrium of allele T of rs4646536 in CYP27B1 was associated with vitamin D deficiency." (PMID 30993743, 2019). "T1D-induced vitamin D deficiency is associated with impairments of renal and extrarenal CYP27B1 and VDR expression." (PMID 29552033, 2018). "The meaning of the allele A in C-1260A of CYP27B1 in active vitamin D deficiency needs further investigations." (PMID 28827564, 2017). "In Cyp27b1 null mice the effect of vitamin D deficiency was reversible, with estrous cycle length and staging normalized with dietary supplementation with vitamin D3." (PMID 25879830, 2015). "This is equivalent to 2.5 fold higher than vitamin D deficient females which had concentrations considered to be above normal given that CYP27B1 expression is increased whereas that for CYP24A1 is decreased under vitamin D deficiency." (PMID 23405058, 2013). "There were associations among NH, vitamin D deficiency and NADSYN1/DHCR7 and CYP27B1 polymorphisms, TT genotype of rs12785878 and GT genotype of rs10877012 could reduce the risk of vitamin D deficiency and NH." (PMID 37259065, 2023). "Moreover, the multivariable regression model revealed that GG genotype of GC-rs7041 and the CA & CC genotypes of CYP27B1-rs10877012 were associated with vitamin D deficiency in the surveyed children." (PMID 35256680, 2022). "Our results suggest that vitamin D deficiency might predispose to maternal cardiovascular risk and perinatal infections especially in male-carrying pregnancies, probably due to lower placental CYP27B1 and cathelicidin expression." (PMID 34578991, 2021).
vitamin D deficiency (continued). "The presence of enzymes CYP2R1 and CYP27B1 and the detection of vitamin D receptor expression in testicular tissue as well as evidence for clinically relevant vitamin D deficiency in hypogonadal men suggested a prominent role of the testis in the metabolism of this vitamin." (PMID 34107893, 2021). "Polymorphisms in CYP2R1 gene could influence vitamin D status in the general population, and CYP27B1 rs4646536 T allele has been shown to be associated with vitamin D deficiency in a family-based study." (PMID 33882819, 2021). "Furthermore, family‐based associations between rs4646536 in CYP27B1 and vitamin D deficiency were also found." (PMID 30993743, 2019). "The results of the pilot case‐control study indicated that both CT and TT genotypes of rs4646536 in CYP27B1 could increase the susceptibility of vitamin D deficiency when compared with CC genotype." (PMID 30993743, 2019). "Thus, we aimed at investigating the family‐based associations of SNPs in CYP2R1 and CYP27B1 with vitamin D deficiency." (PMID 30993743, 2019). "Vitamin D deficiency was accompanied by elevated synthesis of renal CYP27B1 and VDR." (PMID 29552033, 2018). "In addition, the vitamin D metabolizing enzymes (CYP2R1, CYP27A1, and CYP27B1) are also widely expressed in Leydig cells of the testis, and vitamin D deficiency may result in reduced hypogonadism." (PMID 40365228, 2025). "SNPs for CYP27B1 (CA & CC genotype) had statistically significant positive association (β = 1.61; 95% CI 2.79, 0.42; p-value < 0.05) and TT genotype of GC-rs7041 had negative association (β = − 1.33; 95% CI − 0.02, − 2.64; p-value < 0.05) with vitamin-D deficiency in the surveyed children." (PMID 35256680, 2022). "However, SNPs for CYP27B1 and GC-rs7041 were found to be significantly associated with vitamin-D deficiency where SNP for CYP27B1 (β = 1.61; 95% CI 2.79, 0.42; p-value < 0.05) was positively and GC-rs7041 (β = − 1.33; 95% CI − 0.02, − 2.64; p-value < 0.05) was negatively associated with it." (PMID 35256680, 2022). "However, SNP for CYP27B1 was positively associated with vitamin D deficiency suggesting that these SNPs might be a causative factor for vitamin-D deficiency among the surveyed children." (PMID 35256680, 2022). "Vitamin D deficiency, VDR, or CYP27B1 depletion has been shown to cause an increase in Mycobacterium anisopliae and Mycobacterium avium, triggering epithelial barrier dysfunction and intestinal inflammation." (PMID 38549749, 2024). "In the present study, we found that vitamin D deficiency resulted in higher expression of CYP27A1 and CYP27B1, both of which were downregulated when Vitamin D, folic acid, and vitamin B12 were supplemented in the diets." (PMID 36615790, 2022). "On the other hand, vitamin D deficiency in animals (and humans) that lack a functional VDR or cytochrome P450 family 27 subfamily B member 1 (CYP27B1) can be successfully treated by increasing the calcium and phosphate content of the diet." (PMID 34572032, 2021). "The predominant sites of expression of Cyp27b1 mRNA and CYP27B1 protein are TALs, DCTs, and CDs—under conditions of vitamin D sufficiency—and the PCT under vitamin D deficiency." (PMID 32617522, 2020). "Decreased expression of CYP27B1 and VDR, which we established, is most likely a consequence of vitamin D deficiency and inadequate production of the 25OHD prohormone in the liver of diabetic animals." (PMID 29552033, 2018). "Likewise, mice fed a high-fat diet evidenced decrease of vitamin D deficiency, whereas expression of CYP1R1, CYP24A1, and CYP27B1 negatively altered lipid profile and increased lipogenesis." (PMID 37184736, 2023). "We found that CYP27B1 variation might be a predictive factor for vitamin D insufficiency after vitamin D3 supplementation." (PMID 31583252, 2019).
vitamin D deficiency (continued). "Although we did not quantify active vitamin D (calcitriol) or vitamin D metabolizing enzymes (e.g., CYP27B1, CYP24A1), a tissue-level functional vitamin D deficiency could still propagate circadian misalignment and destabilize the otoconial matrix despite normal systemic electrolytes." (PMID 41468411, 2025).
Hypercalcemia (27 papers, 2013 to 2026). An abnormally increased calcium concentration in the blood. "Immunohistochemistry revealed strong CYP27B1 expression in gastric tissue, supporting dysregulated local activation of vitamin D as a mechanism of hypercalcemia." (PMID 41287694, 2025). "We were unable to definitively elucidate the mechanism of hypercalcemia in our case due to the unavailability of PTHrP/CYP27B1 (1-alpha-hydroxylase) immunohistochemical staining and serum assays for PTHrP and 1,25-dihydroxyvitamin D at our institution." (PMID 41479802, 2025). "Together, these findings suggest that both PTHrP-mediated humoral hypercalcemia and CYP27B1-driven vitamin D activation contributed to the patient's refractory hypercalcemia." (PMID 41287694, 2025). "Ketoconazole has been applied in clinical scenarios of steroid refractory hypercalcemia in sarcoidosis due to its allegedly higher potency for extrarenal CYP27B1 inhibition." (PMID 39337491, 2024). "Given the relative stability of calcitriol and persistent hypercalcemia, decreased expression of CYP27B1 likely reflects low PTH levels." (PMID 37311769, 2023). "Similar to Six2-Cre;Sik1fl/+;Sik2fl/fl;Sik3fl/fl mice, only Six2-Cre;Sik2fl/fl;Sik3fl/fl mice showed increased Cyp27b1 expression and serum 1,25-vitamin D levels, mild (but statistically significant) hypercalcemia, and PTH suppression." (PMID 36862513, 2023). "High parathyroid hormone levels and hypercalcemia induce 1,25(OH)2D3 synthesis, stimulating the transcription of CYP27B1 and increasing 1,25(OH)2D3 activity, with consequent down-stream action of CYP27B1 and suppression of parathyroid hormone." (PMID 35458148, 2022). "The hypercalcemia is thought to be calcitriol mediated, where overexpression of CYP27B1 in the macrophages forming the granulomas leads to pathological extrarenal calcitriol production." (PMID 34522373, 2021). "The Epfn KO, MEM1 cKO, and PTH‐CyclinD1 TG mouse models are associated with hypercalcemia, while the CaSR, Cyp27b1, and VDR KO mouse models have a normal serum calcium level despite elevated PTH due to impaired calcium absorption in the kidneys and intestine." (PMID 40164571, 2025). "Notably, the renal 1 alpha-hydroxylase (1α-OHase [CYP27B1]) enzyme is tightly regulated physiologically via feedback loops related to circulating levels of calcium, PTH, and 1,25(OH)2D3 to limit the risk of hypercalcemia." (PMID 39408285, 2024). "Targeted ablation of the fgf-23 gene in mice disrupts calcium, phosphorus and 1,25 (OH)2D homeostasis, giving rise to hypercalcemia, hyperphosphatemia and increased serum 1,25(OH)2D concentrations, the latter due to significantly increased renal expression of CYP27B1 mRNA and protein." (PMID 24019880, 2013). "Thus, the induction of CYP27B1 in these extrarenal tissues is by cytokines, and the failure of CYP27B1 in these tissues to respond to the increased circulating levels of 1,25(OH)2D and calcium account for the hypercalcemia often found in granulomatous diseases, such as sarcoidosis and lymphomas." (PMID 38676447, 2024). "Thus, the induction of CYP27B1 in these extrarenal tissues by cytokines and the failure of CYP27B1 in these tissues to respond to the increased circulating levels of 1,25(OH)2D and calcium account for the hypercalcemia often found in granulomatous diseases such as sarcoidosis and lymphomas." (PMID 32051922, 2020). "HPHPT chief cell patterns show a marked CaSR decreased expression along with an increased CYP27B1/VDR expression, suggesting an appropriate autocrine/paracrine counterregulation to hypercalcemia/high PTH." (PMID 41907687, 2026). "While FGF23 represses CYP27B1 and activates catabolism of active hormone, increased PTHLH secretion can lead to hypercalcemia via inactivation of VDR." (PMID 37242266, 2023). "Global- and kidney-specific Sik2/Sik3 mutant mice showed Cyp27b1 upregulation, elevated serum 1,25-vitamin D, and PTH-independent hypercalcemia." (PMID 36862513, 2023).
Hypercalcemia (continued). "Thus, kidney-specific SIK deletion in mice resulted in Cyp27b1 stimulation, which led to PTH-independent, 1,25-vitamin D–dependent hypercalcemia." (PMID 36862513, 2023). "Our data suggest that engraftment of ectopic CYP27B1 in leukemia bone marrow is critical for both reduction of leukemia blasts and protection of host microenvironment for healthy hematopoietic stem cells’ recovery without systemic hypercalcemia." (PMID 32847594, 2020). "Also, 25(OH)D3 induces hypercalcemia in animals lacking the 1α-hydroxylase (CYP27B1 −/−knock-out) at relatively low doses." (PMID 28039464, 2017). "Renal CYP27B1 is stimulated by the parathyroid hormone (PTH), hypocalcemia and hypophosphatemia and receives negative feedback from 1,25(OH)2D3 as well as hypercalcemia." (PMID 39337491, 2024).